EGFR (epidermal growth factor receptor)
Diseases named in the same sentence as EGFR in open-access papers (continued):
Sharing a sentence is not in itself a finding about the gene and the disease.
tumor (continued). "Previous studies have proven that STX6-mediated intracellular transport of vascular endothelial growth factor 2 (VEGFR2), epidermal growth factor receptor (EGFR), and integrins regulates tumor proliferation, angiogenesis, and metastasis." (PMID 36612024, 2022). "Knockdown of EGFR axis sensitized TCTPhigh tumor cells to CTL-mediated killing, and increased T cell chemotaxis." (PMID 35440620, 2022). "Cell surface receptors, especially those that can serve as targets for therapeutic agents, can be used to identify clinically significant tumor variations; one such example is the epidermal growth factor receptor (EGFR), which controls cell growth." (PMID 35145836, 2022). "These enhancers are rewired in ecDNA to increase oncogene EGFR expression and tumor fitness using CRISPR interference to disable individual enhancer activity revealed a unique mechanism of enhancers in controlling oncogene amplification." (PMID 35614494, 2022). "EGFR is a large molecular weight transmembrane glycoprotein with multiple structural regions that plays an essential role in tumor formation and growth, and it has became the critical target for targeted therapies in various tumors." (PMID 36523491, 2022). "EVs can affect the extracellular matrix (ECM) by modulating tumor immune responses and can even transfer active oncogenes, e.g., epidermal growth factor receptor (EGFR) or the mutant form of Kirsten rat sarcoma virus (KRAS)." (PMID 36500247, 2022). "MEK is a component of the Ras signaling pathway, and when MEK is activated, the EGFR-Ras-Raf signaling pathway is activated, which can eventually lead to tumor resistance to MEK inhibitors." (PMID 35684449, 2022). "Results demonstrated that hCAP18/LL-37 promotes tumor growth mainly by activating the EGFR/HER2/Akt signaling pathway in HCC cells and in xenograft tumors with endogenous overexpression." (PMID 35039485, 2022). "Vascular endothelial growth factor (VEGF), and Epidermal growth factor receptor (EGFR), which act on both tumor and endothelial cell populations, are two of the growth factors that control the angiogenic response in HCC." (PMID 36671388, 2022). "In this regard, agonistic activation of RIG -I by IVT4 was found to increase tumor shrinkage by CD8+ and NK cells in immunocompetent EGFR-driven in vivo tumor models treated with EGFR inhibitors." (PMID 35757716, 2022). "Preclinical and clinical studies showed that EGFR tyrosine kinase inhibitors (TKIs) decrease tumors and improve the overall tumor immune microenvironment." (PMID 36612121, 2022). "In contrast, EGFR expression showed a gradual increase with Gleason score, and the expression in non-tumor samples as compared to tumor samples of any Gleason score was statistically significantly different." (PMID 35804847, 2022). "The increased stiffness of the tumor microenvironment (TME) can promote GBM proliferation by enhancing EGFR signaling." (PMID 35954323, 2022). "In one study, RBC membrane PGLA-coated with gambogic acid (GA) as antitumor drug and modified with recombinant dual surface protein, anti-EGFR-iRGD, as EGFR single domain antibody and tumor penetrating peptide, respectively was developed." (PMID 35590367, 2022). "The epidermal growth factor receptor (EGFR) plays a central role in the tumor microenvironment, through the activation of paracrine and autocrine circuits that promote cancer development and progression." (PMID 35406622, 2022). "The cross-talk between pathways of inflammatory response/prostaglandins biosynthesis and EGFR signaling plays a key role in enhancing the growth and spread of tumor cells." (PMID 36432658, 2022). "Targeting EGFR alone or combination with the conventional cytotoxic agents or castration treatment has shown that optimistic tumor growth inhibition in in vitro cell lines and in vivo xenograft models of PCa." (PMID 35499593, 2022).
tumor (continued). "It has already been shown that hsa-miR-215-5p is frequently downregulated in CRC tissues and exhibits tumor suppressor activity through the regulation of EGFR or WNT signaling pathways." (PMID 35216222, 2022). "In tumor cell lines, the loss of FLCN resulted in slower endocytic trafficking of EGFR by decreased Rab7A GTP-to-GDP turnover, resulting in prolonged and elevated phosphorylated EGFR and downstream signaling." (PMID 35863698, 2022). "While several mechanisms of intrinsic resistance have been reported, the mechanisms underlying the distinct clinical scenario of limited tumor response followed by earlier tumor progression during initial EGFR TKI treatment are less well defined." (PMID 35579943, 2022). "This case agreed with our study, that the inhibitory activity of osimertinib is able to overcome resistance to first-generation EGFR TKIs, as indicated by notable tumor shrinkage in these two patients." (PMID 36626541, 2022). "Further, EGFR-TKIs can also induce a rapid and temporary increase of cytotoxic CD8+ T cells, dendritic cells, and a reduction of the pro-tumor M2-macrophage population in EGFR-driven lung tumor mouse models." (PMID 36074553, 2022). "In a word, PI3K/AKT/EGFR and MAPK signaling pathways play a crucial role in cancer cell proliferation and tumor progression, and a previous study has confirmed that EGFR is a target for TNBC treatment." (PMID 36523491, 2022). "This antibody simultaneously inhibits EGFR signaling, activates T cells and initiates a tumor immune response by blocking the interaction between PD-1 on T cells and PD-L1 on tumor cells, and also induces strong ADCC." (PMID 36185288, 2022). "It was found that GSC tumor showed strong expression of Ki-67, moderate expression of EGFR and VEGF, and weak expression of MGMT and HIF-1α." (PMID 36591483, 2022). "EGFR and iCre clusters were identified as tumor cells and related more to human scRNA-seq categories defined by Johnson-Verhaak9 than those defined by Neftel-Suvà10." (PMID 35624211, 2022). "We next assessed the effects of darifenacin on drug tolerance in 3D culture models of tumor cells derived from EGFR-mutant PDX mice." (PMID 36048538, 2022). "To overcome this barrier, we screened ER-PE24 ITs with an optimal affinity to EGFR to selectively target EGFR-overexpressing tumor cells, while sparing normal tissue cells that express low basal levels of EGFR." (PMID 36555466, 2022). "Extending these studies to animal models, we found that cetuximab was the most effective anti-EGFR agent for reducing tumor burden in mice bearing DSRCT tumors." (PMID 34841430, 2022). "Since EGFR and PD-L1 are widely expressed on healthy cells, simultaneous binding of both proteins is essential to increase tumor-specificity." (PMID 35479092, 2022). "The presence of HER2 mutations in NSCLC is correlated with a “cold” tumor microenvironment, characterized by a relatively lower PD-L1 positive expression rate and tumor mutation burden (TMB), similar to those of EGFR-dependent tumors." (PMID 35425713, 2022). "To date, the gold standard for measuring EGFR and ALK status is mutational sequencing of tumor tissue acquired from biopsy." (PMID 35624472, 2022). "The results presented here demonstrate that the level of EGFR expression correlates with the free uptake of B-ASO by tumor cells and provides for high selectivity compared to normal cells." (PMID 36499115, 2022). "Previous studies have reported that EGFR overexpression contributes to tumorigenesis and tumor progression in the classical subtype of gliomas." (PMID 36347915, 2022). "N-glycosylation is a mediator for the epidermal growth factor receptor (EGFR) signaling pathway and it is via this pathway that the progression of the tumor continues." (PMID 35682652, 2022).
tumor (continued). "In line with previous studies, IRF1 expression was increased in tumours, displaying a proinflammatory immune phenotype upon EGFR inhibition." (PMID 36010935, 2022). "Transforming growth factor-α/epidermal growth factor receptor signaling promotes the occurrence and progression of cancer cells and generates a tumor microenvironment advantageous to metastasis." (PMID 35222525, 2022). "Although systematic investigations are lacking to date, in a patient with a lung squamous cell carcinoma bearing a missense mutation in the ERBB4 gene (p.Arg847His), afatinib showed some efficacy, but the tumor also carried an EGFR amplification." (PMID 36476337, 2022). "It is noteworthy that in most of the cases with EGFR amplification, the tumor was located on the right lung (10/13; 77% of cases EGFR amplified), in line with previous studies." (PMID 35565304, 2022). "When ZEGFR:03115-IR700 was administered i.v., the strong fluorescence signal of the conjugate was detected ex vivo within the brain EGFR-positive lesions (2–3 mm in diameter) as early as 1 h post-injection in mice bearing MRI-confirmed tumours (n = 3)." (PMID 35057796, 2022). "In EGFR-overexpressing tumor xenograft mouse models, the maximum tolerated dose (MTD) of intravenous injection of ER/21-PE24 was found to be 0.4 mg/kg, which was fourfold higher than the MTD (0.1 mg/kg) of ER/0.2-PE24." (PMID 36555466, 2022). "The treatment of hDT806 disrupted EGFR signaling and inhibited cellular transcription, leading to DNA damage, an apoptotic response, and tumor growth inhibition in HNSCC." (PMID 35453686, 2022). "Cetuximab engagement of CD16 activates NK cells and induces IFNγ secretion, an important soluble factor which promotes dendritic cell maturation leading to increased tumor antigen presentation and expansion of EGFR specific T cells." (PMID 36341402, 2022). "The USP6NL level, together with EGFR expression in human GBM tissue samples and cell lines associated with therapy resistance, tumor growth, and cancer invasion, were investigated." (PMID 35884836, 2022). "Initial studies suggested that EGFR was expressed in human UM cell lines and tumours and that the expression correlated with tumorigenic activities, including proliferation and metastatic potential." (PMID 35781872, 2022). "We and others have previously demonstrated reduced IFN-γ gene signature and T cell infiltration in EGFR-mutated NSCLC, which suggests decreased immunogenicity or suppression of immune response in the tumor microenvironment (TME)." (PMID 35132961, 2022). "High expression of SGCE inhibits EGFR degradation via the ubiquitin lysosomal pathway, increases tumor cell drug resistance, and promotes metastasis." (PMID 36467074, 2022). "The constitutive presence of EGFR in the tumor cell nucleus has been reported to be a poor prognostic indicator of invasive breast cancer." (PMID 35013116, 2022). "For example, researchers synthesized an anti-tumor conjugate comprising methoxy-modified EGFR siRNA and cyclo RGD (cRGD) peptides, which selectively bind to αvβ3 integrins." (PMID 35874843, 2022). "Whereas ATM inhibition alone had little effect on tumor growth, EGFR inhibitor monotherapy suppressed the growth of tumors before eventually giving rise to resistance outgrowth." (PMID 35353542, 2022). "For example, only the occipital tumor region showed amplification of the EGFR locus, whereas a PTPN11 missense mutation and ERRFI1 homozygous deletion were exclusively in the parietal tumor region." (PMID 36114166, 2022). "This tetrafunctional antibody results in high tumour selectivity by targeting EGFR and the checkpoint inhibitor programmed death-ligand 1 (PD-L1) simultaneously, and has attenuated CD3ε binding, diminishing the cytokine release and toxicity effects." (PMID 36439165, 2022). "For example, SC4MOL and NSDHL inactivation sensitizes tumor cells to EGFR inhibitors, and DHCR24 heterozygous knockout in mice reduces cholesterol levels without causing health problems." (PMID 35386193, 2022).
tumor (continued). "Both cetuximab and panitumumab compete with epidermal growth factor (EGF) for binding to perturb the downstream signaling of EGFR, thus inhibiting the proliferation of tumor cells." (PMID 35907884, 2022). "And then, these compounds were tested for inhibitory effects against EGFR and tumour cells (A549, PC-3, HepG2)." (PMID 35260020, 2022). "Tumor-bearing mice in the TB-G-N group showed markedly lower levels of p-EGFR, TGF-β, p-AXL, Wnt3a, and β-catenin proteins compared to those in the TB-G group." (PMID 36547898, 2022). "Among the 51 tumors, there was one tumor with EGFR mutations in both the LAMP and the NGS assays, another one with EGFR wild type in the LAMP assay but EGFR mutations in the NGS assay, and the others with EGFR wild type in both assays." (PMID 35744511, 2022). "EMT is a vital factor in tumor cell plasticity and a possible pathway for the generation of drug-resistant cells with mesenchymal properties after epidermal growth factor receptor (EGFR)-targeted therapy." (PMID 35653786, 2022). "It deserves further effort to develop strategies co-targeting NK1R and EGFR as an alternative approach to curb tumor development in NSCLC patients driven by EGFR and/or NK1R." (PMID 35013118, 2022). "EGFR exon 20 insertion status was assessed by either by direct tumor sampling or circulating tumor DNA (ctDNA)." (PMID 34913823, 2022). "PEGylated liposomes conjugated with antibodies against TfR and HIR (PILPs) were loaded with siRNAs directed against the mRNA of telomerase reverse transcriptase (TERT) and EGFR, both involved in tumor growth." (PMID 36297407, 2022). "Scientists have investigated the combination strategy of EGFR-TKIs and other anti-tumor strategy in order to delay drug resistance." (PMID 35525919, 2022). "In the C57 xenograft model, CTM with high EGFR/MET expression was detected in the blood vessels of lung metastasis mice, which was higher than that in tumor tissues, indicating EGFR/MET as a suitable marker for CTC/CTM detection." (PMID 35428350, 2022). "An important observation is that TKIs fail to trigger apoptosis in a fraction of responsive NSCLC tumour cells addicted to EGFR signals, instead inducing G1 cycle arrest." (PMID 35158954, 2022). "It is reported that plasma is a suitable source of tumor-derived ctDNA for the detection of EGFR alterations in lung tumor patients." (PMID 36568152, 2022). "Recently, epidermal growth factor receptor (EGFR) and tyrosine kinase inhibitors (TKI) such as gefitinib and erlotinib, are reported to be effective only in tumours with EGFR kinase domain mutations that are most common in ADC." (PMID 36712764, 2022). "Our study represents an initial step in defining the role of tumor suppressor genes in oncogenic EGFR-driven lung tumors." (PMID 35252550, 2022). "In a concomitant setting SOT101 at 1 nM and the marketed therapeutic anti-CD38 antibody Daratumumab, the anti-CD20 antibody Obinutuzumab or the anti-EGFR antibody Cetuximab at 0.1, 1 and 10 nM were incubated with tumor cells for 20 h." (PMID 36300122, 2022). "As an exemplar, Nan and co-workers prepared versatile nanoplatforms capable of specific codelivery of DOX and cisplatin to tumor sites by utilizing an EGFR-targeted approach." (PMID 36096856, 2022). "Recent studies connect between EGFR activation and immunosuppression, suggesting an additional role for EGFR as a modulator of tumor microenvironment." (PMID 35154483, 2022). "The network pharmacology and pathway enrichment analysis predicted that EGFR, PI3K, and AKT1 was increasingly associated pathway with the anti-tumor properties of 18α-GA in NSCLC." (PMID 36313358, 2022). "We reviewed the scientific literature to retrieve the relevant experiments and biological phenomena related to the tumor growth in EGFR+ LUAD patients and their TTP." (PMID 35796890, 2022). "Analysis of tumor tissue of the three patients who underwent surgery confirmed malignancy and the presence of EGFR amplification." (PMID 34998092, 2022).
tumor (continued). "In this case, combination with an EGFR inhibitor restored sensitivity to alectinib and promoted tumour regression in alectinib-resistant mouse models suggesting that resistance was mediated not by ALK mutations, but rather by upregulation of bypass pathways." (PMID 35884511, 2022). "Tumor cells that persist after the initial EGFR-TKI therapy contribute to the development of TKI resistance." (PMID 36612121, 2022). "Duligotuzumab (MEHD7945A) binds to both HER3 and EGFR, inhibiting signal transduction, leading to the inhibition of tumor proliferation." (PMID 36551663, 2022). "The results suggest that the shedding of tumor-specific EVs containing mutant EGFR DNA is proportional to the tumor burden." (PMID 35681723, 2022). "EGFR overexpression, which occurs as a result, plays an essential role in tumor generation and progression, especially in highly malignant carcinomas." (PMID 36188649, 2022). "EGFR is amplified or overexpressed in a variety of tumor types, and has been validated as an important oncology target." (PMID 35295841, 2022). "EGFR is a transmembrane tyrosine kinase receptor, expressed in a variety of epithelial tumors, and regulates tumor cell growth, invasion, transformation, angiogenesis, and metastasis by activating downstream signal transduction proteins." (PMID 35081265, 2022). "Tumor heterogeneity is a significant reason, yielding various drug resistance mechanisms, such as EGFR‐dependent or ‐independent extracellular signal‐regulated kinase 1 and/or 2 (ERK1/2) activation in NSCLC." (PMID 35838331, 2022). "The present study demonstrated that treatment with dasatinib inhibited platelet adherence to tumor cells, phosphorylation of EGFR and Akt, as well as ERK, resulting in complete reversal of the high D-dimer plasma-induced TKI resistance." (PMID 35756605, 2022). "Accordingly, cell RNA-seq profiles from human EGFR mutant lung adenocarcinomas tumor samples demonstrated that FA metabolism and ROS pathway signatures were gradually increased during treatment from naïve to resistant relapsed tumors." (PMID 35159223, 2022). "Preclinical studies in breast and colorectal carcinoma models demonstrated tumor uptake of 89Zr-nimotuzumab increasing up to 168 h post-injection, and, notably, EGFR expression was clearly visualized as early as 24 h post-injection." (PMID 35326605, 2022). "For instance, aptamers are able to efficiently recognize tumor markers such as nucleolin, mucin, and epidermal growth factor receptor (EGFR)." (PMID 36559056, 2022). "SRC is an effector of the EGFR signaling pathway, which enhances the invasiveness and survival rate of tumor cells." (PMID 35891968, 2022). "Mouse models and the use of therapeutic monoclonal Abs (anti-HER2/neu, -EGFR) in humans have revealed that Abs specific to tumor Ags can kill tumor cells." (PMID 36230721, 2022). "As a result, the CAR exhibits strong in vivoin-vivo and in vitro tumor-killing capacity against EGFR-vIII mutant or EGFR-overexpressing tumor cells, but maintains low toxicity to EGFR normally expressed cells." (PMID 35874698, 2022). "The present study found that BPAF also up-regulated the expression of ERα, GPER1, and EGFR in the hypothalamus, ovary, and uterus of nude mice with SK-BR-3 tumor." (PMID 36497816, 2022). "By contrast, treatment with EGFR CAR T cells led to an upregulation of the adhesion molecule CD54 on tumor cells, with further augmentation upon IL-2 administration." (PMID 35836798, 2022). "In turn, it has been demonstrated that activation of the Hh pathway can promote resistance to EGFR inhibitors, possibly via the induction of tumor cell epithelial-to-mesenchymal transition." (PMID 35752861, 2022). "To summarise, we observed compelling antitumour responses upon blocking oncogenic EGFR signalling with prolonged survival over vehicle tumours." (PMID 36010935, 2022).